MYC (MYC proto-oncogene, bHLH transcription factor)
Diseases named in the same sentence as MYC in open-access papers (continued):
Sharing a sentence is not in itself a finding about the gene and the disease.
breast cancer (continued). "Here we demonstrate for the first time that MYC inhibition by transgenic Omomyc is efficacious against all breast cancer molecular subtypes, including triple-negative breast cancer, where it displays potent antimetastatic properties both in vitro and in vivo." (PMID 36860495, 2022). "Compared to cancers with neutral copy numbers of MYC, breast cancers with amplified MYC contained lower fractions of monocytes, M2 macrophages and CD8+ T cells, whereas they showed increased fractions of M0/M1 macrophages and regulatory T cells." (PMID 36323660, 2022). "Collectively, these data indicated a prominent role of a TET2/MYC cross-talk in controlling lysosomal activity in breast cancer cells and impeding survival upon autophagy induction." (PMID 35351824, 2022). "In conclusion, we have shown that the novel MYC inhibitor MYCi975 decreased proliferation and induced apoptosis in breast cancer cell lines." (PMID 35908121, 2022). "TIMELESS promoted breast cancer progression by activating MYC and regulated cancer cell progression via the Sp1/ACER2/S1P axis." (PMID 35715407, 2022). "USP22 promotes the deubiquitination of c-MYC in breast cancer cells, resulting in increased levels of c-MYC." (PMID 35408841, 2022). "SETDB1 enhances c-MYC and cyclin D1 expression, and thus provides a growth advantage to breast cancer cells." (PMID 35395812, 2022). "The G9a-MYC complex in breast cancer localizes at the p21 and GADD45A promoters to catalyze H3K9 methylation, repressing both MYC target genes." (PMID 35740522, 2022). "NFκB activation in IBC has been reported previously, and MYC and NFκB have been shown to cooperate in breast cancer development and progression, amongst others by modulating stem cell behavior." (PMID 35042871, 2022). "This idea was supported by earlier work showing that the spliceosome is a potential therapeutic vulnerability following MYC induction in 2D breast cancer cells and also during lymphomagenesis." (PMID 35589755, 2022). "TGCA database was used to analyze the expression of miR-3189-3p, c-MYC, 4EPB1, and eIF4E in breast cancer." (PMID 35642054, 2022). "CLK2 has previously been pharmacologically targeted in MYC-driven breast cancer and genetically in GBM." (PMID 35731869, 2022). "For example, in pancreatic and breast cancer cells, MYC expression products bind to and activate the promoters of the pro-apoptotic proteins BIM and BID, thereby facilitating the initiation of mitochondrial responses to apoptotic stimuli." (PMID 36527013, 2022). "Next, we intersected the MYC-bound genes identified by ChIP-seq with the genes downregulated upon MYC overexpression in the mouse mammary tumors, organoids and sorted tumor cells." (PMID 36323660, 2022). "Subsequent work demonstrated that the blockade of the spliceosome leads to intron retention and death of MYC-hyperactivated breast cancers." (PMID 35439169, 2022). "To validate the effect of MYCMI-7 on endogenous MYC:MAX interactions, isPLA was used in MCF7, a breast cancer cell line we have used extensively to validate the effect of MYC:MAX inhibitors on endogenous MYC:MAX interactions." (PMID 36874405, 2022). "USP22 promotes the deubiquitination of c-MYC in breast cancer cells, resulting in an increase in c-MYC level." (PMID 35935969, 2022). "In contrast, hMSCs from both sources enhanced breast cancer cell migration, possibly by increasing the expression of MYC, SNAI1, and TWIST genes in those cells." (PMID 36406002, 2022). "We observed a positive correlation between LPP2 (PLPP2) and MYC mRNA expression in 56 breast cancer cell lines through analyzing the CCLE database." (PMID 35966578, 2022). "The positive feedback loop among DCST1-AS1, miR-873-5p, and MYC contributed to breast cancer cell proliferation." (PMID 36613528, 2022).
breast cancer (continued). "It is possible that the effect of ZNF148 dosage in breast cancer is more pronounced in the context of MYC, stemness, and metastatic state of the cells." (PMID 36207293, 2022). "Targeting both core spliceosomal components in MYC-dependent breast cancer and snRNP assembly through PRMT5 in MYC-driven lymphoma impaired tumourigenicity and implied a therapeutic vulnerability in cancers reliant on oncogenic MYC." (PMID 35014671, 2022). "Recent studies identified MKK3 as hub protein due to its interaction with several molecular partners, including MYC; this interaction was reported to sustain MYC stability supporting breast cancer cells proliferation." (PMID 35158751, 2022). "To investigate if MYC transcriptionally regulates ZNF148 in breast cancer, we first examined the ChIP-seq data in the Encyclopedia of DNA Elements (ENCODE) database." (PMID 36207293, 2022). "In breast cancer, MYC is the most frequently amplified gene, with amplification occurring in 15–40% of cases." (PMID 35908121, 2022). "This is mediated by ligand-independent Erα and PR activation, followed by their induction of MYC expression and was also verified in human breast cancer cells." (PMID 35299741, 2022). "To translate the potential of MYC inhibition in breast cancer to a relevant clinical setting, we made use of three models of TNBC to validate the Omomyc miniprotein therapeutic impact in vivo." (PMID 36860495, 2022). "A potential strategy to bypass the immune-suppressive effects of MYC overexpression in triple-negative and BRCA-mutated breast cancer would be to activate IFN signaling via STING agonists in tumor cells and their environment." (PMID 36323660, 2022). "The BRCA1 gene suppressed basal stem cell expansion during mammary tumor development and downregulated MYC expression, quenching the MYC-driven oncogenic pathways." (PMID 36207293, 2022). "Taken together, these findings suggest that MYC overexpression suppresses inflammatory signaling, supporting breast cancer to evade detection by the immune system." (PMID 36323660, 2022). "miR-769-3p downregulates n-MYC downstream-regulated gene 1 expression and enhances apoptosis in breast cancer MCF-7 cells upon changes in oxygen concentration." (PMID 36139534, 2022). "The potential of MYC for regulating glycolysis in cancers has been indicated in B-cell acute lymphocytic leukemia, colorectal cancer, and breast cancer." (PMID 36033372, 2022). "Several MYC-driven multiple myeloma cells and oestrogen receptor- and/or AR-positive breast cancer cells were also acutely sensitive to AU-15330." (PMID 34937944, 2022). "As a tumor suppressor, TGF-β reduces the breast cancer stem cell population, and cell proliferation via MYC, ID1, and ID3 genes." (PMID 36207293, 2022). "In breast cancer, MYC was shown to directly regulate the transcription of ERN1 by binding to its promoter and enhancer and to cooperate with XBP1, leading to enhanced transcriptional activity." (PMID 35349489, 2022). "Of these 1620 ER+ve breast cancers, amplification of the c-MYC copy number was detected in 7.7% of ER+ve cases (125/1620)." (PMID 35267559, 2022).
breast cancer (continued). "In breast cancer, amplification and overexpression of MYC are frequent in high grade and invasive malignancies and are consistently correlated with poor outcome and early recurrence." (PMID 36860495, 2022). "A main regulator of glutamine-related metabolic rewiring, MYC, facilitates excess glutamine uptake by inducing the expression of glutamine transporters and glutaminemetabolizing enzymes in breast cancers." (PMID 35847977, 2022). "ZNF148 suppressed cell proliferation and migration and was transcriptionally repressed by MYC in breast cancer." (PMID 36207293, 2022). "Gene sets related to metastasis, prostate cancer progression, breast cancer relapse in the brain, MYC targets, and HDAC pathway showed enrichment in the patients with a high E6 ratio." (PMID 36591476, 2022). "These genes belong to the MYC network, regulate cell cycle, proliferation, apoptosis, migration, invasion, and metastasis, and/or are prognostic in breast cancer." (PMID 36860495, 2022). "MYC is a proto-oncogene involved in cell cycle progression and apoptosis; amplification of MYC is observed in numerous human cancers, including breast cancer." (PMID 35428183, 2022). "TET2-mediated oxidation of 5-methylcytosine establishes an antiviral state and contributes to MYC-dependent down-regulation of genes involved in lysosome biogenesis and function in breast cancer cells." (PMID 35351824, 2022). "BUD31 is an MYC-synthetic lethal gene and is a potential therapeutic entry point for human breast cancers." (PMID 34986865, 2022). "To confirm that MYC overexpression has similar effects in mouse mammary tumor cells, we performed live-cell imaging in co-cultures of WB1P and WB1P-Myc tumor-derived organoids and syngeneic mouse splenocytes as well as isolated CD8+ T cells." (PMID 36323660, 2022). "In preclinical studies, dinaciclib showed strong antitumoral activity against breast cancer and B‐cell lymphoma expressing high levels of MYC." (PMID 36214609, 2022). "On the contrary, hMSCs from both sources enhanced breast cancer cell migration, possibly by increasing the expression of the MYC, SNAI1, and TWIST genes in these cells." (PMID 36406002, 2022). "MYC mutations were frequent in gynaecologic cancers (high CN UCEC, 63%), breast cancers (normal BRCA, 61%), and HPV-negative head and neck cancers (NHSC HPV-, 48%)." (PMID 35801728, 2022). "The overexpression of c-MYC can drive the development of ER+ve breast cancer and confer tamoxifen resistance through multiple pathways." (PMID 35267559, 2022). "In HER2‐positive breast cancers, for example, amplification of the MYC locus identified a subgroup of patients with particularly poor prognosis when treated with adjuvant chemotherapy." (PMID 36214609, 2022). "In our previous investigations, we found that CSA was active in vitro and in vivo against breast cancer with the estrogen receptor and the oncogenic c-MYC as possible targets." (PMID 35163434, 2022). "The MYC proto-oncogene (MYC) is one of the most frequently overexpressed genes in breast cancer that drives cancer stem cell-like traits, resulting in aggressive disease progression and poor prognosis." (PMID 36207293, 2022). "This is supported by the positive correlation between LPP2 and MYC mRNA levels found in 56 human breast cancer cell lines and also in human lung, upper aerodigestive tract, and urinary tract cancer cell lines." (PMID 35966578, 2022). "It was demonstrated that elevated lactate production through induced LDHA activity directs USP28-mediated deubiquitination and the stabilization of MYC, thereby promoting stem-like traits in breast cancer." (PMID 36230479, 2022). "In summary, our study adds ZNF148 to a cadre of tumor suppressors that MYC actively represses, particularly in breast cancer." (PMID 36207293, 2022).
breast cancer (continued). "The anti-proliferative and apoptosis-inducing effects of the recently discovered MYC inhibitor, MYCi975 were investigated in a panel of 14 breast cancer cell lines representing the main molecular forms of breast cancer." (PMID 35908121, 2022). "In breast carcinomas, MYC is one of the most frequently dysregulated oncogenes, particularly in BRCA1-mutated, basal-like TNBCs, where MYC amplification is reported in up to 50% of cases." (PMID 36207293, 2022). "HIF-1α can induce pluripotent stem cell inducers, such as OCT4, NANOG, SOX2, KLF4, c-MYC, and microRNA-302, in 11 cancer cell lines (derived from prostate, brain, kidney, cervix, lung, colon, liver, and breast cancers)." (PMID 34064635, 2021). "The proto-oncogene MYC signaling pathway has been found to be significantly expressed in EOBC (≤45 years) compared to late-onset breast cancer (≥45 years)." (PMID 33807872, 2021). "CPT1A is regulated by c-MYC or AMPK in breast cancer, and promotes breast cancer metastasis or therapeutic resistance through several oncogenic signaling pathways, such as VEGF, ERK and Src pathways." (PMID 33858374, 2021). "A recent study reported that MYC induces over-production of 2-HG and DNA epigenetic changes, which were related to a poor prognosis in a subset of breast cancers." (PMID 34436421, 2021). "MYC target V1, mTORC1 signaling pathway, and E2F targets were closely related to the progression of breast cancer." (PMID 34567213, 2021). "Genes including hTERT, HER2 (ERBB2), HRAS, KRAS and c-MYC confer increased proliferative capacity in breast cancer." (PMID 34988459, 2021). "Abnormal expression of c-MYC has been found in most malignant tumors, including breast cancer, colon cancer, cervical cancer, myeloid leukemia, melanoma, osteosarcoma, glioblastoma, small-cell lung cancer, and medulloblastoma." (PMID 34950208, 2021). "MYC was knockdown in different molecular subtypes of breast cancer cells including MCF-7, MDA-MB-231, SKBR3 and JIMT1." (PMID 34803511, 2021). "Previous studies have noted MYC expression as a poor prognostic marker in various cancers, such as breast cancer, osteosarcoma, and pancreatic ductal adenocarcinoma." (PMID 33818013, 2021). "In agreement with this idea, MCF-7 breast cancer cells treated with estrogen E2 favor the enrichment of ERα and MYC at the H2AFZ gene promoter to trigger H2A.Z expression." (PMID 33627784, 2021). "Our study demonstrate that circACTN4 is a novel oncogenic circRNA in breast cancer through activation of MYC and plays an important role in the progression of breast cancer." (PMID 34116677, 2021). "Overexpression of lncRNA EPIC1 is associated with poor prognosis in patients with luminal type B breast cancer, and promotes tumor growth and cell cycle progression by interacting with MYC." (PMID 34116677, 2021). "Several studies implicated PVT1 in aspects of cancer pathophysiology including the observations that rearrangement of the 8q24 region encoding MYC and PVT1 is frequently involved in human prostate, ovarian, and breast cancer." (PMID 33670447, 2021). "The study have shown that the expressions of FUBP1 and its target MYC in breast cancer tissues were higher than those in adjacent normal tissues." (PMID 34116677, 2021). "(E) Representative immunohistochemistry staining of MYC in lung metastases of breast cancer patients (n = 9)." (PMID 34169837, 2021). "Depletion of c-MYC further sensitized different molecular subtypes of breast cancer cells to combined treatment, thus highlighting a key role of decreased c-MYC expression in drug sensitivity." (PMID 34803511, 2021).
breast cancer (continued). "For example, it was reported that the level of plasma c-MYC in breast cancer patients was markedly higher than that of normal control and was related to clinical stage and lymph node status." (PMID 34116677, 2021). "Nearly three decades ago, Indium-111-labeled antisense-oligonucleotides were used to measure MYC mRNA in breast cancer mouse models." (PMID 34637026, 2021). "For example, USP28 has been reported to stabilize MYC and to be highly expressed in colon and breast cancers." (PMID 34272356, 2021). "The role of lactate dehydrogenases in lactate metabolism has been studied extensively in breast cancer, and many have reported that LDHA overexpression is seen under hypoxic conditions and is associated with c-MYC gene overexpression and glutaminolysis." (PMID 34069745, 2021). "We chose intra-vital microscopy of mammary tumor windows to validate our approach in two orthotopic breast cancer models: a MYC-overexpressing, transgenic, triple-negative breast cancer (TNBC) model and a murine model of the 4T1 family." (PMID 33466329, 2021). "Examples of putative breast cancer susceptibility genes identified using eQTL-based approaches include: ABHD8 at 19p13, AKAP12/ESR1 at 6q25.1, and MYC at 8q24." (PMID 34439109, 2021). "was that p62/SQSTM1 improves breast cancer stem-like properties by promoting MYC mRNA stabilization." (PMID 35083142, 2021). "In contrast, AR has been found to increase MYC expression in several PCa cell lines, and in AR-positive apocrine breast cancer cells." (PMID 34911936, 2021). "For instance, in breast cancer, it has been discovered that an MYC (proto-oncogene BHLH Transcription Factor; MYC) is a direct target of the FBXW7 protein, resulting in modifications of MYC protein levels and deregulation of a cell’s cycle." (PMID 34946938, 2021). "The protein contents of both MYC and HIF1α were consistently decreased upon the treatment of echinomycin for 24 h in lung and breast cancer cell lines." (PMID 33572152, 2021). "It has been demonstrated that β-catenin knockout reduces c-MYC expression and increases fatty acid synthesis in the breast cancer cell model MCF-7." (PMID 33808259, 2021). "As a result, increased expression of BCL2 indicated favorable OS and RFS and high expression of MYC had good OS but poor RFS in breast cancer." (PMID 34828282, 2021). "They demonstrated that breast cancer cells secrete EVs containing miR-105 whose expression is under the control of MYC in cancer cells and, once released, miR-105 is able to activate the MYC signaling in CAFs inducing metabolic reprogramming." (PMID 33401522, 2021). "These gene signatures with c-MYC (myc proto-oncogene protein) are frequently overexpressed in poorly differentiated tumors and then well differentiated in breast cancer, glioblastoma, and bladder carcinomas." (PMID 34064635, 2021). "In particular, in breast cancer, c-MYC represents a direct target and coregulatory of ERα, and ERα and c-MYC act synergically to induce cell proliferation." (PMID 33808259, 2021). "MYC has been an attractive therapeutic target for the treatment of breast cancer, whereas a direct inhibition of MYC remains challenging." (PMID 33462336, 2021). "There is one prior study that used hyperpolarized MRSI to measure the glycolytic effects of switching off MYC expression in transgenic mouse models of breast cancer which resulted in tumor regression followed by recurrence." (PMID 34685601, 2021). "MYC pathway deregulation has been determined to play a role in the development, progression, metastasis, and therapy resistance of breast cancer." (PMID 33807872, 2021). "The activity of the MYC transcriptional interactome is frequently deregulated in breast cancer and contributes to mammary tumor development and progression." (PMID 33805424, 2021).